C5 (complement C5)
Diseases named in the same sentence as C5 in open-access papers (continued):
Sharing a sentence is not in itself a finding about the gene and the disease.
COVID-19 (continued). "In addition, a clinical trial (phase 2 study) with zilucoplan (complement C5 inhibitor) is ongoing to assess the efficacy and safety of zilucoplan in improving oxygenation and short- and long-term outcomes in COVID-19 patients with acute hypoxic respiratory failure." (PMID 36232655, 2022). "Thus, C5 blockade by eculizumab might also serve to prevent the thromboembolic complications of COVID-19." (PMID 34928990, 2021). "Indeed, a recent study from Milan, Italy, reported elevated levels of the C5 activation fragment C5a and soluble MAC (sC5b-9) in plasma samples of patients with severe COVID-19, confirming the notion that C5 blockade represents a potentially relevant therapeutic consideration." (PMID 32733489, 2020). "Pronounced expression of complement proteins (C1q, C3, C3b, C4, C5) and inflammatory cytokines (TNF, IL-1α, and IL-17A/E) was detected in the fetal compartment of COVID-19-affected pregnancies." (PMID 39390219, 2024). "Strikingly, administration of C3 (AMY101) and C5 targeting drugs (eculizumab) resulted in marked reduction of pro-inflammatory cytokines and improved lung function in SARS-CoV-2-induced COVID-19." (PMID 36430817, 2022). "Currently several inhibitors of the CS are in clinical trials for COVID-19 treatment (C3: NCT04395456; C5: NCT04355494 and C5a: NCT04346797)." (PMID 34904186, 2022). "Ongoing RCTs that target C5 in severe COVID-19 are evaluating the monoclonal antibodies eculizumab (NCT04346797) and ravulizumab (NCT04570397 and NCT04390464), and peptide inhibitors of C5, such as zilucoplan (NCT04382755)." (PMID 36304162, 2022). "The C5 inhibitors eculizumab (Soliris) and ravulizumab-cwvz (Ultomiris) have both been proposed in the treatment of ARDS in COVID-19." (PMID 33374356, 2020). "The use of monoclonal antibodies against C5 ravulizumab and zilucoplan did not have any statistically significant effect on the course and outcome of COVID-19 in severe patients." (PMID 39457048, 2024). "Our results do not, however, provide evidence that increased levels of C3, C5, and C5a characterize by COVID-19 in contrast to other pulmonary infections." (PMID 37239041, 2023). "A trial (NCT04369469) investigating the C5-blocking antibody ravulizumab in mechanically ventilated COVID-19 patients was stopped due to lack of efficacy, as reported by a press release." (PMID 35945604, 2022). "In conclusion, we identified COVID-19 vaccination as a potential trigger for aHUS onset or relapse in pediatric and adult patients who are not treated with C5 inhibition." (PMID 36531998, 2022). "In brief, despite nonconclusive studies, the available data suggested favorable outcomes in a small number of patients with severe COVID-19 treated either with C1 inhibitor, MASP-2 monoclonal antibodies, compstatin-based complement C3 inhibitor, anti-C5 drugs, or C5a-C5aR1 antagonists." (PMID 34567008, 2021). "The C5 inhibitor eculizumab resulted in recovery and reduced mean CRP levels in four patients with COVID-19, although the global Phase 3 clinical trial evaluating the longer-acting C5 inhibitor ravulizumab was recently discontinued for lack of efficacy." (PMID 34924021, 2021). "Similarly, in previous reports, FGB, FGG, complements C4, C3, C5, C2, C9, and complement C1q subcomponent subunits A, B, and C (C1QA, C1QB and C1QC) were found to be upregulated in the lung tissues of patient with COVID-19." (PMID 38882332, 2024). "Several inflammatory mediators, such as ENPP2, C5, FASLG, VWF, and CSF1, additionally presented a more robust correlation with the core inflammatory networks in the severe group, and these factors were reported as independent significant indicators of severe COVID-19 in previous studies." (PMID 36776879, 2023). "The C5 inhibitor eculizumab was shown not to reduce C5a levels in severe COVID-19 patients." (PMID 37332066, 2023).
COVID-19 (continued). "The inhibition of C3, which is upstream of C5 in the complement cascade, does not appear to be a safe approach for patients with COVID-19, since it could reduce the antiviral response and prevent immunity to other infectious diseases." (PMID 36304162, 2022). "Interestingly, the only patient with complete recovery of renal function even without C5 complement inhibitor therapy (patient 3) was also the only one who presented with a very short history: he had symptoms of COVID-19 ten days prior to presentation with TMA and admission to our center." (PMID 39596538, 2024). "Hence, targeting the C5– C5aR1–GCS glycosphingolipid pathway could protect the SARS-CoV-2-induced development of s severe form of the disease in patients with COVID-19 and GD patients with COVID-19." (PMID 36430817, 2022). "Notably, the C3 inhibitor AMY-101 has been used in four patients with COVID-19, who recovered; the C5 activation inhibitor, eculizumab, as adjunctive treatment in 14 patients, 12 of whom recovered; another anti-C5a antibody (BDB-001) was used in 2 patients with critical COVID-19, who recovered." (PMID 33827897, 2021).
atypical hemolytic-uremic syndrome (51 papers, 2012 to 2026). A rare, genetic thrombotic microangiopathy due to dysregulation of the alternative complement pathway and characterized by the triad of hemolytic anemia, thrombocytopenia, and acute renal dysfunction. "Genetic deficiencies or abnormalities of FH lead to uncontrolled C3 activation and the accumulation of C3 and C5 activation products within the renal glomerulus and cause the rare renal diseases C3 glomerulopathy (C3G) and atypical hemolytic uremic syndrome (aHUS)." (PMID 34112227, 2021). "For other diseases, such as atypical hemolytic uremic syndrome, prophylactic treatment with complement C5 inhibitor (eculizumab) prevents disease recurrence in most patients and dramatically changed outcomes of KTx." (PMID 39497737, 2024). "In humans, Ravulizumab, a monoclonal antibody to complement C5, has been approved for atypical hemolytic uremic syndrome and is being evaluated in early-phase and preclinical studies for reducing renal disorders." (PMID 38590952, 2024). "The complement factor 5 (C5)-inhibitor eculizumab has been established as standard-of-care for the treatment of atypical hemolytic uremic syndrome (aHUS)." (PMID 38898427, 2024). "For example, it can be key in monitoring complement-directed therapy, as has been shown for the C5 inhibitor eculizumab in atypical hemolytic uremic syndrome." (PMID 36451820, 2022). "Eculizumab is an anti-C5 mAb that was initially approved to treat atypical hemolytic uremic syndrome (aHUS)." (PMID 35874775, 2022). "The possibility to block C5 by the use of a monoclonal antibody against C5 in atypical hemolytic uremic syndrome (HUS) has significantly improved clinical outcomes for this patient group." (PMID 35155460, 2021). "For instance, the C5-inhibitor Eculizumab (Soliris) is used for systemic complement inhibition as an established treatment option for several diseases, such as atypical hemolytic uremic syndrome." (PMID 33371261, 2020). "This confirms that C5 complement blockade is effective in treating complement mediated thrombotic microangiopathy/atypical hemolytic uremic syndrome when it is triggered in patients with inflammatory bowel disease." (PMID 31516395, 2019). "Eculizumab, a monoclonal antibody against the C5 complement protein, is currently used in clinical renal injury settings, mainly for atypical hemolytic uremic syndrome (a-HUS), PNH and in C3 glomerulopathy." (PMID 31662004, 2019). "Eculizumab (trade name Soliris), a recombinant humanized monoclonal antibody that inhibits C5 cleavage by the C5 convertase via binding to C5 was recently approved for atypical hemolytic-uremic syndrome (aHUS), a disease that causes abnormal blood clots to form in the kidneys (2011)." (PMID 23233853, 2012). "The C5-specific mAb eculizumab has been used in kidney transplantation to prevent delayed graft function, in antibody-mediated rejection, atypical hemolytic uremic syndrome (aHUS) recurrence, and anti-phospholipid syndrome." (PMID 34131806, 2021). "Several other antibodies targeting C5 are also being developed; for example, LFG316 targets C5 in age-related macular degeneration, while Mubodina is used to treat atypical hemolytic-uremic syndrome (aHUS)." (PMID 29155837, 2017). "BACKGROUND: Atypical hemolytic uremic Syndrome (aHUS), a form of thrombotic microangiopathy (TMA), had a poor prognosis until the development of complement C5-inhibiting monoclonal antibodies, eculizumab and ravulizumab." (PMID 41987101, 2026). "While eculizumab and ravulizumab are also indicated for atypical hemolytic uremic syndrome (aHUS), pegcetacoplan is approved for patients with PNH who remain anemic despite C5 inhibitor therapy." (PMID 40363920, 2025). "Over the past decade, atypical HUS (aHUS) has emerged as a complement‐mediated thrombotic microangiopathy (CM‐TMA), for which novel therapies targeting terminal complement activation are used (e.g., the anti‐C5 monoclonal antibody eculizumab)." (PMID 41281162, 2025).
Sepsis (36 papers, 2009 to 2026). Sepsis is defined as life-threatening organ dysfunction caused by a dysregulated host response to infection. "The presence of C5 and other products resulting from complement activation in the bloodstream, commonly observed in sepsis, signifies a loss of regulatory control over complement activation." (PMID 39445002, 2024). "Concentrations of complement factors C3, C3a, C3c, C5, C5a, and soluble terminal complement complex were assessed in ethylenediaminetetraacetic acid plasma samples collected within 24 h after sepsis diagnosis using enzyme-linked immunosorbent assays." (PMID 36797757, 2023). "The inhibition of C5 cleavage blocked sepsis-induced inflammation, decreased the associated consumptive coagulopathy, and protected organ functions, resulting in improved survival." (PMID 32344575, 2020). "During sepsis the excess activation of C5 has been associated with enhanced secretion of pro-inflammatory mediators in response to TLR ligands such as LPS." (PMID 19308263, 2009). "Likewise, C5 or C5aR-deficient mice were also resistant to developing sepsis in the experimental model of cecal ligation and puncture." (PMID 31687410, 2019). "The decrease in C5a levels may lead to worsened disease outcome as C5-deficient mice demonstrate impaired bacterial clearance and a study of adult patients with sepsis-induced brain dysfunction revealed a correlation between decreased C5a levels with increased mortality." (PMID 32373108, 2020). "Our data suggest that C5 expression might be used as an early marker (day 1 after trauma) for identification of trauma patients at risk for the development of nosocomial infections/sepsis." (PMID 26607226, 2015). "In summation, complement proteins C3 and C5 are pivotal in the onset and progression of sepsis, highlighting the critical connection that inflammasome activation represents between the complement system and coagulation pathways." (PMID 39445002, 2024). "For example, the anaphylatoxins C5a, produced by the complement C5, is the most effective inflammatory peptide and it is strongly activated during sepsis." (PMID 33714207, 2021). "In contrast lipopolysaccharides (LPS)-induced ALI fully developed in C5-/- mice during sepsis compared to complement sufficient animals, suggesting that LPS-induced ALI is rather C5 independent." (PMID 27437704, 2016). "It has been demonstrated that during CLP-induced sepsis, rat receiving anti-C5 antibody showed decreased bacterial load in spleen and liver compared with those receiving control IgG." (PMID 23233853, 2012). "C5a, a protein fragment released from the complement component C5, has also been of interest in the pathogenesis of sepsis-induced cardiac depression." (PMID 22482045, 2012). "Recent studies reported that the complement system may play important roles in sepsis mortality and organ damage: The anti-C5 antibody reduced mortality, bacterial load, and lung injury." (PMID 34200709, 2021). "Concerning complement-targeted therapies in sepsis, application of RA101295, a 2-kDa macrocyclic peptide inhibitor of C5 cleavage, improved organ performance and survival in an E. coli-sepsis model of baboons with lessened evidence of coagulopathy and preserved endothelial and barrier functions." (PMID 30949180, 2019). "Thus, C5 is a particularly interesting target for intervention in sepsis, leaving C3 free to opsonize in microbial defense." (PMID 26612199, 2015). "Recently, the well-defined proinflammatory C5a-C5aR pathway has been targeted for pharmacological therapy via inhibition of C5 cleavage, C5a blocking antibodies or C5aR antagonists for treatment of sepsis, cardiovascular diseases, autoimmune disorders, asthma, and psoriasis." (PMID 24523571, 2014). "In addition, C5 inhibitor attenuated sepsis-increased soluble uPAR, thrombomodulin and angiopoietin-2 in plasma, suggesting that C5 inhibition may also protect against endothelial cell dysfunction." (PMID 32194424, 2020).
Sepsis (continued). "Noteworthy, combined inhibition of C5 activation and CD14 attenuated more robustly hypercoagulability in sepsis." (PMID 37081895, 2023). "We aimed to investigate associations between the key molecules in the terminal complement pathway, C3, C3a, C3c, C5, C5a, and soluble TCC (sTCC), and the dysregulated immune response in sepsis patients." (PMID 36797757, 2023). "According to a recent investigation, baboon survival was enhanced, coagulopathy was decreased, and endothelial and barrier function were maintained in an E. coli‐induced sepsis model through the utilization of RA101295, a C5 peptide inhibitor." (PMID 38020710, 2023). "The effectiveness of the complement inhibition therapies at the C3 level (compstatin) and C5 level (RA101295), along with CD14 inhibition monotherapy were already proven to be beneficial in porcine and baboon sepsis models." (PMID 36059503, 2022). "In the present study the role of C5 as a main component of the complement system was determined in a DH model of ALI induced by blunt chest trauma and subsequent polymicrobial sepsis." (PMID 27437704, 2016). "Blocking C5 and the protein receptor cluster of differentiation 14 (CD14), which binds TLR-4, abolishes the inflammatory response and improves survival in sepsis models." (PMID 26420913, 2015). "Specifically, activation of C5 can increase TF expression on leukocytes and blockade of C5a-ameliorated DIC in a rodent model of sepsis." (PMID 23320021, 2012). "It is therefore implied that a C5 blocking antibody should not be used in acute inflammatory diseases which are microbial driven, such as sepsis and others." (PMID 22482043, 2012). "In a model of severe sepsis in pigs due to infusion of live E. coli, administration of a neutralizing monoclonal anti-pig C5a antibody (not cross reactive with C5) led to significantly decreased levels (75%) of IL-6." (PMID 22482043, 2012). "C5 activation products (C5a anaphylatoxin and the membrane attack complex [MAC] C5b-9) are generated during sepsis following infusion of endotoxin, or after cecal ligation and puncture (CLP), which produces polymicrobial sepsis." (PMID 21170490, 2010). "Activation of the complement cascade (components C3 and C5) was detected in the kidneys in our sepsis patients, but could not be detected in any other tissue." (PMID 37731199, 2023). "Furthermore, C5-/- mice were not able to form the terminal MAC, displayed in absence of hemolytic complement activity (CH-50) associated with reduced systemic bacterial clearance (400-fold) and tremendous bacterial load in C5-/- mice in sepsis." (PMID 27437704, 2016). "In lung tissue cytokine and chemokine concentrations were elevated 36 hrs after blunt chest trauma and 12 hrs after induction of sepsis by CLP in both presence and absence of C5 suggesting that CLP-sepsis acts as a relevant systemic second hit to maintain and reinforce inflammation in the lungs." (PMID 27437704, 2016).
meningococcal infection (24 papers, 2015 to 2025). Infections with bacteria of the species neisseria meningitidis. "The anti-C5 monoclonal antibody Eculizumab binds to C5, thereby preventing cleavage into its active components, but has been associated with a thousand-fold increased risk of meningococcal disease." (PMID 31293600, 2019). "Similar to genetically mediated C5 deficiency, functional C5 deficiency created by eculizumab increases the risk of Neisseria meningitidis infection." (PMID 27135055, 2015). "Persons who use complement inhibitors: Use of complement inhibitors (e.g., the currently licensed eculizumab [Soliris] and its long-acting derivative ravulizumab [Ultomiris] monoclonal antibody therapies that block C5) is associated with a substantially increased risk for meningococcal disease." (PMID 33417592, 2020). "Since eculizumab prevents the terminal complement pathway through inhibition of C5 cleavage, and Neisseria meningitidis is primarily eliminated by the terminal complement components, patients treated with eculizumab are at increased risk of meningococcal infections." (PMID 38809358, 2024). "Hence, if the SSL7 C-terminal domain (SSL7-CT) was used to block C5 cleavage, the risk of meningococcal disease could be lower than with existing anti-C5 therapeutics." (PMID 30555486, 2018). "While bacterial infections, particularly meningococcal disease, are well-established risks of C5 inhibition, viral infections have garnered less scrutiny." (PMID 40860872, 2025). "Caution to avoid serious infectious complications, particularly meningococcal infections with C5 inhibitors, remains of paramount importance." (PMID 40565949, 2025). "The age association reflects broader trends of increased infection severity in older populations, while the C5 inhibitor link may relate to severe bacterial risks (e.g., meningococcal infections) or differences in patient demographics and exposure duration." (PMID 40860872, 2025). "Although the manufacturer recommends antibiotics only for 15 days after vaccination, if vaccination was not possible before, we recommend using prophylactic antibiotics (against meningococcal disease) while the patient is under C5 inhibitor treatment (grade 1A)." (PMID 39918340, 2025). "C5 deficiencies result in the inability to generate the MAC, elevating the risk of recurring Neisseria meningitidis infections and a rare condition known as recurrent meningococcal disease." (PMID 37809154, 2023). "On the other hand, while C5-deficient mice displayed higher susceptibility to Neisseria meningitidis infection, the lack of C5aR1 contributed to a favourable outcome ameliorating inflammatory cytokine response more rapidly than wild-type mice." (PMID 31687410, 2019). "Moreover, iptacopan may allow for a more effective immune response to meningococcal infection in vaccinated individuals than anti-C5 antibody therapy." (PMID 37441479, 2023). "Selective inhibition of C5-cleavage by the AP C5-convertase, and not the CP C5-convertase, may partially preserve serum bactericidal activity, thereby lowering the risk of meningococcal disease." (PMID 33570492, 2021). "In addition, measurable protective antibody titers will decrease the risk of meningococcal disease, but not fully prevent it and protection from vaccination-induced antibodies is questionable under eculizumab-induced C5 blocking by in vitro studies." (PMID 32159209, 2020). "Since eculizumab, the first complement drug now used in the clinic, does not specifically block C5 activation on target cells, its inhibitory effects on solution phase C5 may predispose patients to serious meningococcal infections." (PMID 26552476, 2015). "No relapses, deaths, or severe infections—including meningococcal disease—were reported, supporting the safety of anti-C5 therapy." (PMID 41333025, 2025).